CD4 (CD4 molecule)
Diseases named in the same sentence as CD4 in open-access papers (continued):
Sharing a sentence is not in itself a finding about the gene and the disease.
tumor (continued). "The predominance of CD4+ T cells in tumor-infiltrating immune cells of CRC metastases to the lungs has been found to be associated with a better outcome after surgical resection." (PMID 32488850, 2020). "In contrast, the cytokine secretion levels from tumor-infiltrating CD4+ T cells were comparable between SMF-treated mice and control mice." (PMID 32884074, 2020). "Major components of the tumor immune architecture are CD8+ and CD4+ T cells that can essentially contribute to tumor elimination." (PMID 32194568, 2020). "In particular, a therapeutic DNA vaccine must be able to generate both a CD8+ response, which directly kills infected or tumor cells, and a CD4+ helper response, which is able to increase and maintain the cytolytic response." (PMID 33114220, 2020). "Low-density CD3 and CD8 IHC tumours were then further stratified by the addition of CD4 IHC (threshold of 100 positive cells per mm2)." (PMID 32684627, 2020). "It is also decisive for the promotion of either CD4+ T regulatory cells or CD8+ cytotoxic T cells, which is important because CD4+ cells were found to limit the anti-tumor effects of IL-2, while CD8+ cells promote these outcomes." (PMID 33027905, 2020). "Clinicopathological factors, tumor-infiltrating lymphocytes (TILs), CD4+ and CD8+ T cells, and granzyme B (GZB) expression in resected HCC, and postoperative overall and progression-free survival were compared between the three groups." (PMID 32075608, 2020). "With an increase in the risk score, the fractions of tumor-infiltrating immune cells (CD8+ T cells, B cells, neutrophils, macrophages, CD4+ T cells, and DCs) decreased." (PMID 33330624, 2020). "Increased percentages of PD-1+ CD8+ T cells, TIM-3+ CD4+ T cell subpopulations, Tregs and pro-tumor phenotype GAMs substantially contribute to the local immunosuppressive microenvironment in DA." (PMID 32117733, 2020). "As a result, the activated CD4+ T cells promote antitumor immune responses by secreting IFNγ that triggers macrophages and NKs, blocks angiogenesis, regulates the tumor stroma formation, and leads to direct tumor cell lysis." (PMID 33228747, 2020). "In further analysis of the infiltration of immune cells, we found that compared with the control group, anlotinib and combination treatment group significantly inhibited the aggregation of CD45+ CD4+ CD25+ FoxP3+ T cells in the tumor tissues." (PMID 32366856, 2020). "Given the effects of VVΔTKΔN1L on systemic T and NK populations, the VVΔTKΔN1L neoadjuvant therapy regime was repeated in LLC flank tumor-bearing mice in which NK, CD4+ or CD8+ T cells were selectively depleted." (PMID 32217766, 2020). "A key aspect is to identify tumor antigens which optimally stimulate CD4+ T helper cells, as these cells are crucial to triggering and maintaining all effector mechanisms of the adaptive immune response." (PMID 33138029, 2020). "Despite the recognition that MHC-II is significant for tumor neoantigen presentation and priming of CD4+ T cells and for immunotherapy outcomes, the accuracy and precision of MHC-II epitope predictions are poor when compared to class I." (PMID 32117226, 2020). "It is also negatively related to tumor purity, infiltrating levels of CD4+ T cells, neutrophils, and dendritic cells." (PMID 33324448, 2020). "CD4 + T lymphocytes are important for priming tumor-specific CD8 + TILs as well as for the secondary expansion and memory of CD8 + TILs." (PMID 32222891, 2020). "Tc effector function is similarly complicated and shaped by the spatiotemporal distribution of APCs in the tumor milieu and tumor-draining lymph nodes, cytokines and the presence of other immune cells such as regulatory CD4+CD25hiFoxP3+ T (Treg) cells." (PMID 33008037, 2020). "The malignant Reed-Sternberg (RS) cells in CHLs, which comprise only a small portion of the total tumor mass, depend upon growth factors provided by surrounding CD4 T cells (such as CD40L) to proliferate." (PMID 32542010, 2020).
tumor (continued). "Infiltration was often highly variable between different cancers; for example, the most extreme variation was seen with stromal CD4+ lymphocytes occupying from 0.5% to 80% of tumour stromal area." (PMID 32577938, 2020). "Consistently, “good” bacteria introduction was reported to significantly increase IFN-γ production in spleen and tumor-draining lymph nodes (TDLN) and induce DCs to secrete IL-12, resulting in increased recruitment of CCR9+CXCR3+CD4+ T cells into tumor beds." (PMID 33194652, 2020). "IRF family regulates type-I IFN system for anti-tumor immunity through promoting differentiation of B cells, inducing differentiation of naive T cells to effector CD4+ or CD8+T cells and driving the expression of MHC class I and II." (PMID 32508531, 2020). "CD4+ T cells were depleted with the anti-CD4 antibody clone GK1.5 in A20.GL tumor-bearing mice before and after CD8+ m1928z-CD40L CAR T cell treatment." (PMID 33268774, 2020). "In contrast to αCTLA-4-mediated Treg depletion, which is tumor specific, DT depletes Treg cells systemically, promoting general activation of CD4+ and CD8+ T cells in both dLNs and tumors." (PMID 31924474, 2020). "This study challenges existing notions of the pro-tumor roles of type 2 IL4-mediated CD4+ T cell responses and underscores the importance of further detailed mechanistic studies in the TNBC TIME." (PMID 33374595, 2020). "It is important to evaluate the clinical importance of both CD8 T cells and CD4 T cells expression simultaneously because they have crucial networks in tumour targeting immune responses." (PMID 32277125, 2020). "Overall, a significant increase in the tumor-infiltrating leukocytes, from 5 to 30%, was detected, mainly represented by lymphocytes, including CD4+ and CD8+ T-cells and bone marrow-derived monocytes." (PMID 33212945, 2020). "CD4+ T cells can also induce humoral responses against tumor antigens primarily through increased expression of CD40 ligand that promotes differentiation and maturation of B-cells into affinity-matured, class-switched plasma cells." (PMID 33383959, 2020). "Both pro-tumor MΦ2-macrophages and, anti-tumor NK-cell and Th17/CD4+T cell subsets have shown enhanced expression of P-gp." (PMID 32195185, 2020). "Mice receiving wild-type T cells showed a higher tumor load compared with mice receiving TGF-β-DNR transgenic CD4+ T cells." (PMID 32451418, 2020). "Cytokines produced during DC activation influence the immune responses, generating subtypes of CD4+ T cells such as T helper 1 (Th1) cells, Th2 cells, regulatory T cells, or tumor-reactive CD8+ cytotoxic T cells." (PMID 33260400, 2020). "Based on previous observations, we postulated strong antitumor potential of tumor-redirected CD4+ T cells transduced with an HLA class I-restricted TCR against a STEAP1-derived peptide." (PMID 32610710, 2020). "Twenty four hours after injection, the frequency of CD25+ Helios+ population among CD4 T cells in the tumor was enumerated by flow cytometry." (PMID 33117369, 2020). "CD4 T cells was the dominant immune cell type in the tumor area while other immune cells (CD8, CD21) were less frequent." (PMID 33633728, 2020). "In detail, statistically significant shorter survival times occurred in dogs with a total higher immune cell infiltrate as well as higher numbers of CD3+ T cells, CD4+ T cells or tumor infiltrating macrophages." (PMID 32824521, 2020). "A major mechanism of tumor-induced immunosuppression is the recruitment and/or induction of CD4+ regulatory T cells (TREGS) within the tumor microenvironment." (PMID 32299365, 2020). "In this context, it was previously reported that a high presence of tumour infiltrating lymphocytes (TILs), especially intraepithelial CD4+ and CD8+, correlates significantly with improved outcome." (PMID 33097745, 2020).
tumor (continued). "Infiltrating immune cells in primary uveal melanoma include CD4+ T cells, CD8+ T cells, regulatory T (TReg) cells, and Tumor associated Macrophages (TAMs) with the immunosuppressive M2 phenotype." (PMID 33317028, 2020). "In this respect, data indicate that IL-7 administration following cyclophosphamide preconditioning supports the expansion of polyfunctional tumor-specific CD4 T cells." (PMID 32973794, 2020). "Myeloid cells expressing the granulocytic marker (GR-1) were found in abundance in PDAC tumor tissues while CD4+ and CD8+ cells were present in small numbers." (PMID 32656079, 2020). "Daily administration of this strain before and after cancer induction significantly decreased tumor frequency, increased CD4+ and CD8+ T cells in tumor tissues, and decreased TNFα in the serum." (PMID 32523887, 2020). "In this sense, tumours observed in Tdp2−/−Atm−/−mice were also predominantly formed by double positive CD4+ CD8+ T-cell precursors (80%)." (PMID 32060399, 2020). "CD4+ cells include helper T cells, monocytes, and macrophages, which have various functions in tumor progression." (PMID 33081727, 2020). "Mice with restricted growth of rtTERT-expressing tumor cells exhibited CD4+ and CD8+ T cell response against epitopes of rtTERT that are recognized by DNA-immunized mice." (PMID 32570805, 2020). "LUAD patients harboring STK11 mutations were shown to have low densities of CD8+ TILs in tumor beds, in contrast to STK11 wildtype LUAD patients who displayed high levels of CD4+ and CD8+ T cells." (PMID 32117295, 2020). "Combination therapy promoted IFNγ production by CD4+ T cells in the tumor and CD8+ T cells in the spleen and granzyme B production by CD8+ T cells in the tumor." (PMID 33256806, 2020). "Interleukin-35 (IL-35), a member of the IL-12 cytokine family, is produced by Treg cells in tumours, where it promotes CD4+ and CD8+ T cell exhaustion." (PMID 32290500, 2020). "The CD4 mRNA level was modestly elevated but the CD8 mRNA level was significantly suppressed in the tumor-bearing Atg7ΔHep liver." (PMID 32382012, 2020). "A regional comparison for each tumor showed that CD4+ and CD8+ T-cell density were higher in the IM regions than in the IT and PS regions (P = 0.016 for CD8+ T-cell density in PGC, and P = 0.008 for CD4+ T-cell density in MGC)." (PMID 32868848, 2020). "In previous studies, CD4+ T cells and tumor cells engineered to secrete IL-4 have been shown to have potent antitumor effects." (PMID 31937346, 2020). "After long-term exposure to inject exosomes from MKN-45 cells, mice developed an immunosuppressive tumor microenvironment in the lung with increased frequency of effector memory CD4+ T and MDSC, decreased CD8+ T cell and NK frequency." (PMID 32901082, 2020). "Compared to those on CD4+ T cells in PBMCs, the expression levels of antitumor (TNFβ, T-bet, and granzyme B) and protumor (PD-1 and IL-10) markers on CD4+ T cells in tumor sites were commonly higher." (PMID 32117733, 2020). "One frequently used targeted molecule in these combinations is LAG-3, which is a CD4-like molecule expressed by tumor infiltrating lymphocytes (TILs), by activated CD4 and CD8 T cells, Tregs, B cells and DCs." (PMID 32443877, 2020). "Tumor cells secrete angiogenic factors in response to different stimuli, among which, one of the most important is the interleukin 17 (IL-17), a CD4+ T-cell-derived cytokine." (PMID 32133045, 2020). "Concomitant with a significant anti-tumor response at day 21 post-initiation of bintrafusp alfa treatment, there was an increased CD4+ and CD8+ T-cell presence per milligram tumor in bintrafusp alfa compared to control treated animals." (PMID 32373533, 2020). "In contrast, MHC II identifies tumor antigen peptides to CD4+ T helper cells, which trigger cell-mediated immunity." (PMID 32733246, 2020). "MC38 model selection was based on the presence of baseline TIGIT protein surface expression on CD8+ and CD4+ tumor infiltrating lymphocytes." (PMID 33117369, 2020).
tumor (continued). "In a recent paper, CD4 memory, CD8 effector, T helper cell, dendritic cell, and NK cell, which are associated with tumor infiltration, are reported to increase in ccRCC tissues." (PMID 33274196, 2020). "The CD39 and CD73 expression on CD4+ T cells revealed a higher CD4-mediated immunosuppressive capability within the subcutaneously grown tumor 21 days after tumor induction." (PMID 33383676, 2020). "In the tumor, the CD4+ T-cell compartment was characterized by very low proportions of naive cells and relatively high proportions of Eff Tregs and memory Tconvs12,30." (PMID 32601304, 2020). "IL-10 inhibits CD4+ T-cell response induced by mesothelin, an immunogen involved in promoting metastasis and tumor proliferation and a potential therapeutic target in PC." (PMID 32012917, 2020). "TNF released by activated CD4+ T cells in tumor-bearing mice drives emergency myelopoiesis and generation of both monocytic and granulocytic myeloid cells with immunosuppressive properties." (PMID 33363012, 2020). "One possibility is that anti-tumor IgGs produce locally increase antigen presentation by DCs and/or directly promote the activity of specific subsets of CD4+ T-cells endowed with Fcγ receptors (FcγRs)." (PMID 32276524, 2020). "In another study, high tumor infiltration by CD4+ and CD8+ T cells, while low infiltration by Treg cells, and a high ratio of M1 versus M2 macrophages, significantly correlated with longer survival in patients." (PMID 33022971, 2020). "CD4+ memory T cells impede the progression of tumor cells by supporting the proliferation of CD8+ cells, which move to tumor-related tissues and differentiate into effector cells." (PMID 33680920, 2020). "CD4+ T cells in the tumor microenvironment were divided into two subgroups of Th1 cells and Th2 cells according to the phenotype." (PMID 32595698, 2020). "Despite the opposite roles of T-bet and Foxp3 in the immune system and tumour biology, recent studies have demonstrated the presence of CD4+ T cells expressing both T-bet and Foxp3." (PMID 32680511, 2020). "Our results showed that the expression levels of PD-L1 in tumor tissues correlated positively with expression levels of cytolytic granule components (perforin and granzyme B) in peripheral blood CD4+ T and CD56dim NK cells." (PMID 33267869, 2020). "We detected tumor infiltrating CD4+, CD8+ and FOXP3+ T cell proportion in TILs of ILT4-high or ILT4-low patients respectively." (PMID 32368343, 2020). "For example, CD20+ lymphocytes were significantly rarer than CD4+ lymphocytes in both stroma and tumour nests (p < 0.05)." (PMID 32577938, 2020). "Genetic instability of micrometastatic tumour cells and/or changes in the immune system, such as differences in the ratio between cytotoxic CD8 T-lymphocytes and regulatory CD4 T-regulatory cells, being implicated." (PMID 33209110, 2020). "CD4+ cytotoxic T cells can directly kill senescent tumor cells by recognizing MHC II molecules, which are usually absent in healthy cells but present in a subset of tumor or senescent cells." (PMID 32164335, 2020). "Presence of tumor in all three models lead to a reduction in CD4+ T cells, with a greater proportion of these cells being FoxP3+ Treg cells within the spleens of mice bearing NXS2 tumors." (PMID 33028899, 2020). "Accordingly, combination therapy caused a reduction in tumor weight and infiltration of CD4+ and CD8+ T cells into the tumor tissue." (PMID 32707869, 2020). "Combining the nMOF with photodynamic therapy led to tumor regression, and the further addition of anti-PD-L1 antibody significantly expanded CD4+ and CD8+ CTL populations." (PMID 32355277, 2020). "Among the tumor infiltrating immune cells, the CD4 memory activated T cells showed a strong and positive associated with CD8 T cells, whereas resting dendritic cells were moderately associated with resting mast cells." (PMID 33194633, 2020).
tumor (continued). "The main finding was that the transferred exosome from breast and colon cancer cells prevented tumor growth by stimulating CD4 and CD8 dependent T cells." (PMID 33235701, 2020). "The treatment with P2Et, αPD-L1 or P2Et plus αPD-L1 significantly increased the number of CD45+ cells per mg of 4T1 tumor, with an increase in CD4+ and CD8+ T cells." (PMID 33312174, 2020). "CD4+ T cells are responsible for tumor initiation and progression, and naïve CD4+ T‐cell differentiation as well as balance of Th1/Th2 phenotype modulation is important in the modulation of tumor microenvironment." (PMID 32994998, 2020). "The cytotoxic CD8+ T cell population, supported by CD4+ T helper (Th1) cells through the production of IL2 and IFNγ, generates the final effector mechanism leading to tumor elimination and are associated with a good prognosis." (PMID 32423420, 2020). "While Th1 demonstrated anti-tumor capabilities, type 2 CD4 T helper (Th2) were found to be enriched in HCC tissues as compared to normal healthy livers and were inversely associated with OS of HCC patients." (PMID 33117354, 2020). "The discovery of Th17 subset of CD4+ T lymphocytes, distinct from Th1 and Th2 cells was followed by exploration of their role in the tumor microenvironment." (PMID 32850361, 2020). "In early research of NK-based CAR against HIV, CD4-TCRζ CAR-modified NK cells were shown to effectively kill either NK-resistant tumor cells expressing the relevant ligand, gp120, or CD4+ T cells infected with HIV in vitro." (PMID 32903563, 2020). "CD4+ lymphocytes were the most prevalent subtype in tumour stroma and at tumour edge and CD8+ lymphocytes were most prevalent in tumour nests; FoxP3+ lymphocytes were rarest in all compartments." (PMID 32577938, 2020). "CD4+ T cells have also been suggested to be critical for tumor regression during checkpoint inhibitor therapy." (PMID 32226429, 2020). "CD4+ T cells can directly kill tumor cells via cytolytic mechanisms or produce cytokines such as IFNγ which promote anti-tumor immune responses." (PMID 33013886, 2020). "The same study also showed that the MDM2 inhibitor in syngeneic models enhanced anti-tumor immunity in the tumor microenvironment via T-cell proliferation, enhanced CD4 + T-cell activation and increased M1 macrophages." (PMID 32655895, 2020). "Next, we evaluated the levels of circulating CD8+ and CD4+ cells as another alternative of immunological regulation of tumor reduction." (PMID 32244885, 2020). "The numbers of naïve CD8+, and CD4+ T cells are constant in central and tumor-draining lymph node compartments." (PMID 32533270, 2020). "The shIDO-ST + ICB treated tumors have significantly higher numbers of tumor-infiltrating CD4+ and CD8+ T cells compared to all other treatment groups (p < 0.0001), as well as significantly higher numbers of CD11c+ cells." (PMID 33339195, 2020). "The cytofluorometric analyses of single-cell suspensions obtained from tumors collected after brachytherapy showed slight differences in the tumor-infiltrating CD4+, CD8+ and NK cells levels compared to the control tumors." (PMID 32605154, 2020). "Next, the potential correlation of OAS members and tumor immune cells (B cells, CD4+ T cells, CD8+ T cells, neutrophils, macrophages and dendritic cells) was estimated based on TCGA data." (PMID 32560641, 2020). "The dendritic cells, M1 macrophages, and activated CD4 T memory cells that exhibited anti-tumor capacities were all demonstrated higher infiltration in females, compared to the male." (PMID 33083119, 2020). "We observed high levels of tumor‐infiltrating T‐cell subsets, including CD8+ T cells, CD4+ T cells, CD4+FOXP3+ T cells and DNT cells, were associated with prolonged OS and RFS." (PMID 32377339, 2020).